MIF (macrophage migration inhibitory factor)
Diseases named in the same sentence as MIF in open-access papers (continued):
Sharing a sentence is not in itself a finding about the gene and the disease.
African trypanosomiasis (4 papers, 2014 to 2022). "Hence, by both attracting and activating monocyte/macrophages, MIF may contribute to the initiation and perpetuation of detrimental inflammation associated with diseases such as African trypanosomiasis." (PMID 29497418, 2018). "We investigated herein the role of MIF, an upstream regulator of the inflammatory response, in the immunopathogenicity of experimental African trypanosomiasis." (PMID 25255103, 2014). "In the T. brucei African trypanosomiasis model, the suppressive effect of MIF was observed at the later stage of erythroid differentiation." (PMID 25255103, 2014). "Together, this review aims at summarizing the current knowledge on the opposite immunopathological molecular “Yin-Yang” switch roles of MIF and IL-10 in the modulation of the host immune microenvironment during infection, and more particularly during African trypanosomiasis as a paradigm." (PMID 35464430, 2022). "The pivotal role of MIF within the African trypanosomiasis model regarding the persistence of inflammation might be multifactorial." (PMID 29497418, 2018). "Furthermore, given the unmet medical need of African trypanosomiasis affecting millions of people, these findings highlight MIF as a potential new therapeutic target for treatment of trypanosomiasis-associated pathogenicity." (PMID 25255103, 2014). "Neutrophils can represent an important source of MIF and so far their contribution to African trypanosomiasis remains unknown." (PMID 25255103, 2014).
astrocytoma (4 papers, 2023 to 2025). "Compared to the IDH-mutant astrocytoma, GBM exhibited increased information flow in multiple pathways including GALECTIN, COMPLEMENT, MIF, SPP, and PTN." (PMID 38012322, 2023).
cerebral infarction (4 papers, 2017 to 2025). An ischemic condition of the brain, producing a persistent focal neurological deficit in the area of distribution of the cerebral arteries. "Other studies of MIF in the CNS showed that MIF depletion was neuroprotective in a cerebral infarct model without changing the quantity of accumulating macrophages but by altering their surface expression." (PMID 29084983, 2017). "Moreover, in the MIF knockout mice, the expression level of pro-inflammatory markers and CD74+ cells was not affected by the absence of the MIF after cerebral infarction." (PMID 35805977, 2022).
Chagas disease (4 papers, 2012 to 2025). A parasitic infection caused by Trypanosoma cruzi. "MIF (macrophage migration inhibitory factor) −173C allele and CC genotype were related to the major risk of Chagas disease in the Colombian and Peruvian populations." (PMID 24069594, 2013). "The only study that addressed this issue demonstrated that the MIF-173G/C polymorphism confers susceptibility to Chagas disease in two cohorts from Colombia and Peru." (PMID 22496958, 2012). "In the context of Chagas disease, MIF has demonstrated significant potential as a biomarker for progressive chronic cardiomyopathy." (PMID 40092999, 2025). "Early MIF induction by macrophages in chagas disease has been reported to play an important role in providing resistance against T. cruzi infection by promoting the production of IL-12, IL-18, IL-6, TNF-α, IL-1β, IFN-γ, NO and ROS during acute infection." (PMID 40092999, 2025). "In Chagas disease, early MIF induction in target tissues from infected hosts has been reported as a crucial step for resistance to acute T. cruzi infection." (PMID 23451183, 2013). "Furthermore, circulating MIF levels in T. cruzi-infected individuals showed a very significantly positive correlation (r = 0.75, P<0.0001) with the amount of HS-CRP, a serum biomarker linked to serious heart pathology in Chagas disease." (PMID 23451183, 2013). "However, at present there are no studies demonstrating a contribution of MIF to human mortality in Chagas disease." (PMID 22496958, 2012). "Even though MIF elevation is not exclusively related to CCC, it may be complementary to other inflammatory markers for evolution of Chagas disease to more advanced stages of cardiovascular impairment." (PMID 23451183, 2013).
chronic pancreatitis (4 papers, 2014 to 2021). A chronic inflammatory process causing damage and fibrosis of the pancreatic parenchyma. "MIF has proven to be essential in this process, but requires further validation as a prognostic biomarker, which calls for clinical studies that link elevated levels of MIF in patients with chronic pancreatitis to the development of liver metastases." (PMID 29903049, 2018). "Chronic pancreatitis tissues showed a stronger MIF staining than normal pancreata both in islets, glands and ducts." (PMID 24708788, 2014). "The protein and mRNA levels of MIF in paraffin-embedded human PC samples, chronic pancreatitis specimens, and normal pancreas were measured by immunohistochemistry and quantitative reverse-transcriptase polymerase chain reaction." (PMID 24708788, 2014). "We did not identify original study investigating MIF and chronic pancreatitis." (PMID 33776775, 2021).
Cirrhosis (4 papers, 2019 to 2023). A chronic disorder of the liver in which liver tissue becomes scarred and is partially replaced by regenerative nodules and fibrotic tissue resulting in loss of liver function. "Nevertheless, these data indicate that MIF exerts detrimental influences on the hepatic micromilieu and hepatocyte function/differentiation in cirrhosis and during hepatic carcinogenesis in contrast to its effect during fibrogenesis." (PMID 31370326, 2019). "While genotypes associated with higher MIF expression could be associated with decreased severity during the course of fibrogenesis, implicating a protective effect of MIF on fibrosis progression, the pictures seem to be inverted as soon as cirrhosis is established." (PMID 31370326, 2019). "In the healthy state, the communication probability exhibited by the MIF signaling pathway was insignificant, similar to that of IL16 in the cirrhosis state." (PMID 36221095, 2022). "In our cohort, the atypical chemokine-like factor MIF was present at higher concentrations in NAFLD sera, particularly in sera from patients with cirrhosis, whereas its concentration was lowest in sera of patients with HCC in cirrhosis." (PMID 38015590, 2023). "PoPH macrophage clusters also demonstrated a unique signature, with increased CXCL2 and CD163 expression, and diminished MIF expression, relative to non-PoPH cirrhosis macrophage clusters." (PMID 37558836, 2023).
clear cell renal cell carcinoma (4 papers, 2014 to 2024). "In vitro studies on MIF/CD74 (CD44) knockdown by siRNA approach, as reported for clear cell renal carcinoma, shed light on this aspect." (PMID 24939415, 2014).
diabetic retinopathy (4 papers, 2010 to 2025). "MIF may play a role during the proliferative phase of diabetic retinopathy by activating and retaining intraocular macrophage." (PMID 27280065, 2016).
end-stage renal disease (4 papers, 2015 to 2022). "We recently showed that MIF is a plasma component that can be dialyzed effectively during hemodialysis in chronically ill patients suffering from end-stage renal failure." (PMID 27313864, 2016). "We recently showed that hemodialysis is an effective tool to neutralize circulating MIF by removal from the blood pool in patients with end-stage renal failure." (PMID 27313864, 2016).
epilepsy (4 papers, 2020 to 2025). A brain disorder characterized by episodes of abnormally increased neuronal discharge resulting in transient episodes of sensory or motor neurological dysfunction, or psychic dysfunction. "MIF is also involved in various pathologies: infectious, autoimmune and neurodegenerative diseases, epilepsy and others." (PMID 34662363, 2021). "In line with this study, MIF was also found to be up-regulated in the frontal cortex and in the hippocampus of rats subjected to kainic acid-induced epilepsy." (PMID 32259116, 2020). "In addition, MIF is involved in different neurodegenerative diseases, including epilepsy." (PMID 34662363, 2021). "However, elevated MIF in the plasma may contribute to the detrimental autoimmunity, neuroinflammation and epilepsy." (PMID 34662363, 2021).
gingivitis (4 papers, 2019 to 2025). A disorder involving inflammation of the gums; may affect surrounding and supporting structures of the teeth. "The results of our study showed that among the chemokines associated to macrophage functions, salivary levels of MIF were significantly higher in participants with gingivitis than the ones with healthy gingiva." (PMID 36747174, 2023). "On the contrary, the MIF level was higher (13.50 ± 1.26) among gingivitis cases as compared to healthy subjects (10.83 ± 1.93), a statistically significant difference of 2.67 was detected with p < 0.001." (PMID 36747174, 2023). "The difference in MCF and MIF levels between patients with gingivitis and those with healthy periodontium was statistically significant (p 0.05 and p 0.001, respectively)." (PMID 36747174, 2023). "Another study noticed that gingivitis patients with and without metabolic disorders had equivalent Gingival Crevicular Fluid (GCF) MIF levels, and similar to our results MIF levels were higher in the gingivitis group compared to the healthy group." (PMID 36747174, 2023). "In addition, MIF produced higher AUC (0.891) value to discriminate gingivitis patients from healthy subjects, when compared to others." (PMID 36747174, 2023). "The results from the present study suggested that MIF scores above 12.5 could be plausibly considered to be indicative of gingivitis." (PMID 36747174, 2023). "We found that salivary MIF levels were higher in gingivitis subjects than the participants with healthy gingiva and the difference in mean MIF levels between healthy and localized gingivitis and healthy and generalized gingivitis group was statistically significant (p < 0.0001)." (PMID 36747174, 2023). "Hence, the aim of this study is to compare the salivary levels of MAF, MCF, and MIF in periodontally healthy and gingivitis patients, and correlate levels of these chemo attractants with clinical gingival inflammation levels." (PMID 36747174, 2023). "Our results suggest that MIF could be considered as a potential salivary biomarker for gingivitis." (PMID 36747174, 2023). "However, very few studies were done to investigate MAF, MIF, and MCF biomarkers in saliva for early diagnosis of gingivitis and progression of periodontal disease." (PMID 36747174, 2023). "On the other hand, we were not able to detect any impact of 14 days of oral hygiene neglect on the salivary IL-1β, IL-8, MIF, or MCP-1 levels in either the placebo or the probiotics groups, which is contrary to our earlier study where IL-1β, IL-8, and MCP-1 decreased during experimental gingivitis." (PMID 38004199, 2023).
hypothyroidism (4 papers, 2014 to 2025). Abnormally low levels of thyroid hormone. "A study published in 2014 showed that MIF levels were significantly higher in HT patients than in healthy people and were associated with hypothyroidism." (PMID 39936101, 2025). "The top five hub genes associated with hypothyroidism are ALB, MAPK1, SPP1, PPARG, and MIF, whereas those associated with hyperthyroidism are ALB, FCGR2B, CD44, LCN2, and CD74." (PMID 32500465, 2020). "After PPI network construction, the top five hub genes associated with hypothyroidism were extracted, including ALB, MAPK1, SPP1, PPARG, and MIF, whereas those associated with hyperthyroidism were ALB, FCGR2B, CD44, LCN2, and CD74." (PMID 32500465, 2020). "Serum levels of MIF were significantly higher in patients with overt hypothyroidism than the euthyroid patients (p = 0.036)." (PMID 25506398, 2014). "Serum levels of MIF were higher in patients with overt hypothyroidism (6300.9 ± 2504.3 pg/ml) than the euthyroid patients (3955.2 ± 3013.6 pg/ml) (p = 0.036)." (PMID 25506398, 2014). "Although the difference was not significant, we found higher MIF levels in patients with overt hypothyroidism compared to the euthyroid and subclininal hypothyroid patients and healthy subjects (p = 0.098)." (PMID 25506398, 2014).
Infertility (4 papers, 2012 to 2025). "Additionally, significantly higher serum MIF levels were found in stage III-IV patients with active lesions but not in those with chronic fibrotic conditions associated with infertility and pelvic pain." (PMID 40724945, 2025). "In our study, there was a significant difference in serum MIF between fertile endometriotic patients and those with either primary or secondary infertility." (PMID 32883256, 2020). "Moreover, in patients presented with pain and infertile patients showed significantly higher levels of serum MIF (1.92 ± 1.13 vs 1.21 ± 1.17 and 1.82 ± 1.13 vs 1.32 ± 0.91 respectively with p-value < 0.001)." (PMID 32883256, 2020). "Although several studies have proposed the co-relationship between infertility and semen NO and MIF concentrations, no study on the effects of scrotal heat stress (SHS) has been reported." (PMID 26512992, 2015).
ischemic cardiomyopathy (4 papers, 2017 to 2025). Ischemic cardiomyopathy is a cardiomyopathy in which a weakness in the muscle of the heart due to inadequate oxygen delivery to the myocardium with coronary artery disease being the most common cause. "Among patients with non-ischemic cardiomyopathy, myocardial MIF expression was elevated in those with chronic myocarditis and correlated with the degree of myocardial fibrosis." (PMID 40092999, 2025). "Furthermore, macrophage migration inhibitory factor (MIF; the inflammatory cytokine) mediates the pro-inflammatory effects that lead to fibrotic remodeling in HF due to non-ischemic cardiomyopathy with reduced LVEF." (PMID 35205062, 2022). "MIF and HIF-1α mRNA expression was analyzed in myocardial samples from patients with ischemic (ICM) and non-ischemic cardiomyopathy (NICM) and from patients after heart transplantation (HTX)." (PMID 29027966, 2017).
kidney infection (4 papers, 2012 to 2025). "Our study revealed the elevation of the urinary MIF level in APN patients with kidney infection, and urinary MIF serves as an injury biomarker of AKI in these patients." (PMID 23319831, 2012). "We therefore evaluated the diagnostic utility of the urinary MIF, IL-1β, and KIM-1 levels as biomarkers for AKI during kidney infection." (PMID 23319831, 2012). "In summary, we found that the urinary MIF level is significantly elevated in AKI patients during kidney infection." (PMID 23319831, 2012). "Therefore, the aim of this study was to investigate the ability of aberrant urinary MIF levels to detect AKI in patients with kidney infections." (PMID 23319831, 2012). "In patient with normal renal function on arrival (defined as eGFR ≥60 mI/min/1.73 cm2, n = 18), our result revealed an elevated urinary MIF indicating the presence of kidney infection compared to normal controls (4.7 ± 3.8 ng/mg versus 0.7 ± 0.5 ng/mg, P < 0.001)." (PMID 23319831, 2012).
kidney inflammation (4 papers, 2015 to 2026). "Results showed that CD74 and MIF were up-regulated in glomerulus of anti-Thy1 nephritis on day 7 and decreased by AZD8797." (PMID 40458609, 2025). "Overall, they substantiated our data by confirming that elevated urinary MIF was, in fact, mainly due to active inflammation and that urinary MIF could serve as a potential marker of kidney inflammation and a potential therapeutic target in patients who fail to respond to steroids." (PMID 40968277, 2026). "An initial report found no protection from ureteral obstruction-induced kidney inflammation or fibrosis, but an abstract indicated that MIF targeting promoted interstitial fibrosis and inflammation following ureteral obstruction, whereas recombinant MIF reduced fibrosis." (PMID 26441987, 2015).
malignant glioma (4 papers, 2012 to 2022). A grade III or grade IV glioma arising from the central nervous system. "In malignant gliomas, autocrine MIF counteracted NK and cytotoxic T‐cell‐mediated tumour immune surveillance." (PMID 35060345, 2022). "Considering data from clinical studies as well, MIF expression also has predictive values, as patients with malignant gliomas and high MIF expression levels show worse prognosis and earlier tumor recurrence." (PMID 22973314, 2012). "Also, MIF transcripts were elevated up to 800-fold in malignant glioma cells compared with normal brain." (PMID 29707160, 2018). "Nevertheless, it needs to be unambiguously demonstrated whether MIF is primarily effective in an autocrine or intracellular manner in malignant gliomas." (PMID 22973314, 2012).
metastasis (4 papers, 2015 to 2024). The spread or migration of cancer cells from one part of the body (where they first appeared) to another. "Briefly, elevated MIF expression was significantly associated with tumor stage (p < 0.0001), lymph node metastasis (p = 0.0002), distant metastasis (p = 0.0175) and the survival rate of patients (p = 0.0447) but not with other clinicopathological parameters, including age and sex." (PMID 35036405, 2021). "Measurement of exosomal MIF levels in patients with stage 1 PDAC revealed a correlation of high exosomal MIF levels with the development of liver metastasis as compared to patients with low exosomal MIF." (PMID 27088079, 2015). "It is worth noting that MIF expression is higher in exosomes from stage I PC patients who later develop liver metastasis, indicating that exosomal MIF might be a prognostic biomarker of PC liver metastasis." (PMID 33803470, 2021). "Patients with stage I PDAC who later developed liver metastasis showed a significant increase in MIF compared with those without tumor progression, indicating the important role of exosomal MIF in liver metastasis and its potential as a prognostic marker for predicting liver metastasis." (PMID 39596226, 2024).
ovarian tumor (4 papers, 2010 to 2024). "Hagemann reported that MIF expression increased in both borderline and malignant ovarian tumor cell lines compared to normal tissue." (PMID 38534733, 2024). "MIF is also an important regulator of the host innate immunity induced by pro-inflammatory states such as PCOS and ovarian tumors, and it has been associated with various immunological events in the process of oocyte development." (PMID 35668784, 2022). "Macrophage migration inhibitory factor (MIF) produced by ovarian tumor cells decreases the transcription and expression of the activating receptor NKG2D on NK cells thereby inhibiting their ability to recognize and lyse ovarian tumor targets." (PMID 20089172, 2010).
pancreatic adenocarcinoma (4 papers, 2021 to 2026). "Other study shows MIF induced by hypoxia in pancreatic adenocarcinoma is necessary for maximal hypoxia-induced HIF1α expression." (PMID 38685050, 2024). "In addition to CXCL12, other factors such as macrophage migration inhibitory factor (MIF), pancreatic adenocarcinoma upregulated factor (PAUF), and ubiquitin have been reported to activate the CXCR4 receptor." (PMID 35008248, 2021).